MSTN (myostatin)
Diseases named in the same sentence as MSTN in open-access papers (continued):
Sharing a sentence is not in itself a finding about the gene and the disease.
GNE myopathy (1 paper, 2018). "Burch and colleagues have measured the serum myostatin concentration in seven genetic neuromuscular disorder patient populations including GNE myopathy." (PMID 29720219, 2018). "However, further studies investigating larger patient cohorts would be helpful to determine the utility of myostatin as a reliable blood biomarker for GNE myopathy." (PMID 29720219, 2018). "Hereby, myostatin level correlated with clinical measures of disease progression in GNE myopathy." (PMID 29720219, 2018).
hypercortisolism (1 paper, 2015). "The overall effects of these actions on myostatin, miR-27a, and SMAD3 would be difficult to predict at present, but these findings might be implicated in the pathogenesis of glucocorticoid-induced muscle atrophy characteristic for hypercortisolism." (PMID 26161091, 2015).
hypogonadotropic hypogonadism (1 paper, 2022). Abnormal ovarian or testicular function due to insufficient hormonal stimulation from the hypothalamic-pituitary axis. "A study involving men with hypogonadotropic hypogonadism, in turn, found myostatin muscle expression decreased by 29 ± 12% after 22 weeks of traditional testosterone replacement therapy (250 mg testosterone every 2 weeks), but serum myostatin did not change." (PMID 36422286, 2022). "Interestingly, this study observed that men with hypogonadotropic hypogonadism had approximately half the serum myostatin concentrations compared with eugonadal men (2.23 ± 0.23 vs 4.0 ± 0.5 ng/mL)." (PMID 36422286, 2022).
IgA nephropathy (1 paper, 2020). "Tubulointerstitial MSTN was expressed in 44 ± 5% of DN specimens but only in 10.5 ± 2% of IgA nephropathy and FSGS samples (p < 0.01)." (PMID 32286342, 2020).
iron deficiency (1 paper, 2022). "We demonstrated that intracellular iron deficiency in myocytes is associated with the highest expression levels of myostatin, atrogin-1, and MuRF1, which comprise the critical factors for muscle atrophy." (PMID 36139428, 2022). "Although no molecular mechanism was evident, ferroportin-induced iron deficiency increased the expression of DAX1, an orphan nuclear receptor in myocytes, and DAX1 was found to be a novel transcriptional regulator of myostatin expression." (PMID 36139428, 2022).
limb girdle muscular dystrophy type 2I (1 paper, 2014). "Also, we have recently demonstrated that severely affected patients with limb girdle muscular dystrophy type 2I (fukutin-related protein deficiency) have a significant ongoing regeneration of muscle and increased levels of myostatin and MAFbx and MuRF1." (PMID 24963862, 2014).
limb ischemia (1 paper, 2016). A ischemia that involves the limb. "The fact that in our model, limb ischemia or T2D per se raised the myostatin compared with the non-diabetic/non FAL animals, is also of interest, since no related reports are available on this protein in the muscle in CLI models in the absence of stem cell implantation." (PMID 28217409, 2016).
lipidosis (1 paper, 2025). "Hence, myostatin inhibition could enhance liver function at baseline or prevent liver dysfunction (i.e., hepatic lipidosis and/or glycogen hepatopathy in T1D)." (PMID 40429969, 2025).
membranous nephropathy (1 paper, 2023). "This article focuses on deciphering the effect of myostatin (MSTN) on podocyte apoptosis in membranous nephropathy (MN) and fathoming out its underlying mechanism." (PMID 36969728, 2023).
mineral bone disorders (1 paper, 2021). "In arterial vessels, experimental evidence indicates that myostatin may mostly promote vascular inflammation and premature aging, while activin-A is involved in the pathogenesis of vascular calcification and CKD-related mineral bone disorders." (PMID 34440838, 2021).
morbid obesity (1 paper, 2020). An excess of body weight, normally defined as an individual with a body mass index greater than 35 or a body weight greater than one hundred percent of ideal body weight. "Higher circulating myostatin levels or gene expression have been found in obese animals and patients with morbid obesity." (PMID 32316563, 2020).
motor neuron diseases (1 paper, 2022). "The aim of this review is to describe the myostatin pathway and its role in motor neuron diseases, and to summarize and critically discuss preclinical and clinical studies of myostatin inhibitors in SMA and ALS." (PMID 35727341, 2022).
Muscle spasm (1 paper, 2020). Sudden and involuntary contractions of one or more muscles. "Muscle spasms were reported in the single‐dose study with the anti‐myostatin antibody domagrozumab, in addition to headache, fatigue, and upper respiratory tract infections." (PMID 33264516, 2020).
Myalgia (1 paper, 2013). "The type I muscle fibre-specific satellite cell response may be due to higher repetitive load in myalgia cases than in healthy controls and the repetitive work mainly being performed by type I muscle fibres may then have increase their satellite cell pool due to the downregulated myostatin." (PMID 23509827, 2013).
Myocardial fibrosis (1 paper, 2023). "This suggests that myocardial fibrosis and myostatin may not be the only factors responsible for the ventricular dysfunction typical of this disease, thereby highlighting the need to explore other potential research targets." (PMID 37958492, 2023).
myosarcomas (1 paper, 2019). "Our findings suggest that MSTN may be a very promising therapeutic target for the treatment of myosarcoma caused by abnormalities in skeletal muscle development." (PMID 30717351, 2019). "However, low expression or absence of MSTN leads to neither excessive muscle growth nor myosarcoma, which involves unrestricted muscle development." (PMID 30717351, 2019). "However, the MSTN-KO cells would not form myosarcomas, but undergo normal apoptosis." (PMID 30717351, 2019).
ovary disorders (1 paper, 2022). "Understanding the normal and pathological role of intraovarian MSTN, particularly concerning granulosa cell functions and follicular fluid levels, may inform novel approaches to fertility regulation as well as enhance the diagnosis and treatment of ovarian diseases." (PMID 35780124, 2022).
polymyositis (1 paper, 2023). A rare idiopathic inflammatory myopathy characterized by symmetric proximal muscle weakness and elevated muscle enzymes. "The first one included Polymyositis (PM), DM and IMNM patients and showed decreased circulating myostatin levels, as we observed." (PMID 36168256, 2023).
scoliosis (1 paper, 2023). A congenital or acquired spinal deformity characterized by lateral curvature of the spine. "Next, myostatin knockout zebrafish were crossed twice with piezo111aa del/+ to examine the relationship between increased muscle mass and scoliosis severity." (PMID 38259612, 2023). "Therefore, disrupting the myostatin gene in piezo111aa del/11aa del fish can easily be used to study the relationship between muscle mass and the pathological level of scoliosis." (PMID 38259612, 2023).
sleep disorder (1 paper, 2022). A change from the patient's baseline sleeping pattern, in the hours slept and/or an alteration/dysfunction in the stages of sleep. "Moreover, sleep disorders could reduce the secretions of testosterone, which could upregulate the expression of myostatin and Regulated in Development and DNA Damage responses 1 (REDD1), promoting protein proteolysis." (PMID 36434541, 2022).
SMA type 1 (1 paper, 2024). "In all of these cases, myostatin levels at the 12-month follow-up remained at the detection threshold of the method, including in a SMA type 1 patient for whom treatment with nusinersen was initiated on the same day as baseline sample collection." (PMID 38487549, 2024). "Seven patients with SMA had myostatin levels at the detection threshold of the method, with four out of the seven being patients with SMA type 1 aged between 3 and 8 years, all in advanced stages, and one out of the seven being a patient with SMA type 3 with a disease duration of 38 years." (PMID 38487549, 2024).
transient cerebral ischemia (1 paper, 2017). "More recently, we also showed that myostatin expression was markedly increased in skeletal muscle 3 days after transient cerebral ischemia in mice." (PMID 29070788, 2017). "Our results demonstrate that subcutaneous injection of PINTA745, an anti-myostatin PINTA745, improves body weight recovery and increases skeletal muscle mass 15 days after transient cerebral ischemia." (PMID 29070788, 2017).
cancer (141 papers, 2009 to 2026). A tumor composed of atypical neoplastic, often pleomorphic cells that invade other tissues. "For example, loss of myostatin expression in some cancers correlates with tumor progression and metastasis." (PMID 40880457, 2025). "Research has demonstrated that systemic overexpression of myostatin in adult mice induces severe muscle and fat loss, resembling the cachexia observed in human cancer patients." (PMID 40104495, 2025). "A recent study demonstrated the protective effect of myostatin inhibition by attenuating soluble ActRIIB, which prevented not only skeletal muscle loss but also cancer-induced cardiac muscle atrophy." (PMID 37755304, 2023). "Imbalance in the myostatin—Smad2/3 pathway causes muscle atrophy, which, in the context of cancer, is called cancer cachexia." (PMID 35457038, 2022). "MSTN is regarded as a therapeutic target for preventing the muscle wasting associated with chronic diseases like cancer." (PMID 35457038, 2022). "Blockade of myostatin and activins in experimental models was found to prevent or attenuate muscle wasting associated with different diseases, including cancer, renal failure, heart failure, metabolic diseases, immobilization and sarcopenia, to name a few." (PMID 33671024, 2021). "Treating cancer-associated cachexia by means of myostatin inhibition has been another field of interest." (PMID 33802348, 2021). "Our mathematical findings suggest that after blocking the myostatin/activin A pathway, partial recovery of cancer-induced muscle loss requires the activation and proliferation of the satellite cell compartment with a functional differentiation program." (PMID 32605273, 2020). "Strikingly, our data are in line to previous results from patients with cancers, where low Myostatin levels were associated with an increased long-term mortality." (PMID 32784522, 2020). "Follistatin by antagonizing myostatin has been shown to exert anti-atrophic effect at least in a specific subset of cancer-bearing mice, the inhibin-deficient ones." (PMID 33255345, 2020). "Myostatin expression and activity are enhanced in experimental cancer cachexia, with inhibition sufficient to reduce muscle loss." (PMID 32423395, 2020). "Myostatin has been found to be associated with cancer cachexia and its expression is stimulated through the JAK/STAT pathway." (PMID 33329046, 2020). "TNF-α and myostatin play important roles in muscle atrophy associated with cancer cachexia and various chronic diseases." (PMID 32267872, 2020). "Cancer mediated activation of the ActRIIB-ALK4/5 heterodimer by myostatin is strongly associated with muscle wasting." (PMID 31285507, 2019). "Chronically elevated STAT3 activity can lead to downstream activation of myostatin and the ubiquitin proteasome system, as observed in cancer cachexia models, causing protein degradation and loss of muscle mass." (PMID 29897957, 2018). "Cancer-associated changes in the circulating levels of activin family ligands, including activin A, activin B, myostatin and GDF-11, are known to exert effects on muscle and bone homeostasis, thus contributing to the development of overt cachexia." (PMID 29089584, 2017). "In cancer cachexia, the most promising therapeutic approach is based on the inhibition of the myostatin pathway to rescue muscle loss." (PMID 26668061, 2015). "Currently, blockade of myostatin function is believed to be a promising therapy against muscle wasting caused by neuromuscular disorders, cancer, and aging." (PMID 24474938, 2013). "In this regard, muscle wasting in experimental cancer cachexia was recently suggested to be associated with myostatin upregulation." (PMID 21048967, 2010). "Similarly to myostatin, high levels of activin A (ActA) have been reported to cause muscle wasting in rodents and have been associated with cancer-related cachexia in humans." (PMID 35454797, 2022).
cancer (continued). "Thus, it is believed that increased MSTN expression is responsible for the progression of cancer and cancer-associated cachexia." (PMID 35812316, 2022). "Therefore, agents that block the myostatin signaling pathway have the potential to treat human disease associated with cachexia e.g. cancer, chronic kidney disease and chronic heart failure, as well as neuromuscular diseases." (PMID 29079832, 2017). "Zhou indicated that activation of ActRIIB (receptor for activin and myostatin) contributes to the loss of mass in cancer cachexia model mice and that an ActRIIB antagonist may be a therapeutic approach to the treatment of cancer cachexia." (PMID 24273513, 2013). "The profound effects of myostatin loss on muscle mass have brought significant attention and effort to this growth factor as a potential therapeutic target for indications in which muscle wasting is a prominent feature, including sarcopenia, cancer cachexia, muscular dystrophies and disuse atrophy." (PMID 30481286, 2019). "For example, MSTN inhibitors can effectively alleviate cancer cachexia symptoms, and the combination of anti-interleukin-6 treatment with immune checkpoint blockade therapy can produce a significant synergistic therapeutic effect." (PMID 42094205, 2026). "In cancer cachexia, elevated levels of myostatin and activin A correlate with reduced markers of bone formation." (PMID 40869331, 2025). "Clinical trials using anti-myostatin antibodies have reported increases in muscle mass and lean body mass in cancer patients with sarcopenia, along with improvements in functional performance." (PMID 40104495, 2025). "Decorin is of particular therapeutic interest because of its synergistic action against myostatin-mediated muscle breakdown and inflammation in cancer cachexia." (PMID 40869331, 2025). "Myostatin overexpression has been observed in patients with chronic diseases, including cancer, and its dysregulation disrupts protein turnover in skeletal muscle, exacerbating CAC‐related muscle atrophy." (PMID 40810552, 2025). "MSTN is a negative regulator of skeletal muscle growth that when overactivated can cause muscle atrophy, systemic inflammation and—along with TGF-β—cancer-associated cachexia." (PMID 39746900, 2025). "Studies using myostatin-null mice and pharmacological agents like ACVR2B-Fc have shown myostatin inhibition preserves muscle mass in cancer cachexia." (PMID 40519290, 2025). "It is worth noting that in two recent narrative reviews of biomarkers in cancer cachexia, both discussed using objective measures of the skeletal muscle wasting process, such as activin A and myostatin." (PMID 38783477, 2024). "We have earlier reported that under the influence of cancer conditioned media mimicking the cancer microenvironment, CVMSCs express a variety of anti-proliferative proteins such as IL-27, MSTN, and TGF-β2, and pro-apoptotic proteins including IFN-α2 and FASLG." (PMID 37298519, 2023). "In regard to cancer cachexia, myostatin plays an integral role in muscle mass regulation, potentially contributing to accelerated muscle loss in this catabolic condition." (PMID 37755304, 2023). "Levels of myostatin (MSTN or GDF8) are abundant in skeletal muscle, linked to muscle wasting and elevated in cachectic cancer rodents." (PMID 37629186, 2023). "ActA retains similar actions with myostatin, since it utilises the ActRIIB receptor, and thus regulates the cancer-related muscle atrophy and cachexia." (PMID 38136400, 2023). "Although inhibiting myostatin/activin A raises interest in the development of drugs to prevent muscle wasting-related cachexia, the roles of myostatin/activin A in cancer cachexia still need further investigation." (PMID 37217930, 2023). "Factors secreted by muscles, such as myostatin and GDF15, or factors secreted by cancer-associated immune cells initiate a series of processes that cause cancer cachexia." (PMID 37217930, 2023).